ZEB1 (zinc finger E-box binding homeobox 1)
Diseases named in the same sentence as ZEB1 in open-access papers (continued):
Sharing a sentence is not in itself a finding about the gene and the disease.
Peritoneal Fibrosis (3 papers, 2019 to 2024). Disorder characterized by a wide range of structural changes in PERITONEUM, resulting from fibrogenic or inflammatory processes. "In this context, the link between miR-200a and its target genes (Zeb1 and Zeb2) in rats with peritoneal fibrosis related to peritoneal dialysis was investigated." (PMID 39968362, 2024). "We have found that miR-200a is down-regulated in a rat model of PD-related peritoneal fibrosis (PF) and could inhibit transforming growth factor beta 1 (TGF-β1)-induced epithelial-mesenchymal transition (EMT) in peritoneal mesothelial cells by target ZEB1/2." (PMID 30888602, 2019).
preeclampsia (3 papers, 2021 to 2025). Preeclampsia is a hypertensive disorder of pregnancy that is characterized by new-onset hypertension with proteinuria presenting after 20 weeks of gestation, and depending on mild or severe forms may initially present with severe headache, visual disturbances, and hyperreflexia. "Therefore, we thought that inhibiting ZEB1 activity could exacerbate preeclampsia, as it might cause the dysfunction of trophoblasts." (PMID 34002673, 2021). "In patients with preeclampsia, the IGF-1 (insulin-like growth factor 1) expression was significantly reduced compared with healthy pregnancy, associated with a downregulation of ZEB1." (PMID 41463130, 2025). "One study showed that IGF-1 may inhibit the development of preeclampsia by decreasing miR-183 expression by increasing ZEB1 expression." (PMID 41463130, 2025).
prostate adenocarcinoma (3 papers, 2017 to 2025). "A recent report demonstrated that high ZEB1 expression directly correlates with high Gleason grade prostate adenocarcinoma that is also demonstrated by our analysis." (PMID 29206234, 2017). "Consistently, the co-expression analysis in TCGA PanCancer Atlas revealed that SCAND1 and MZF1 expression was negatively correlated with EMT driver genes, including CTNNB1, ZEB1, ZEB2 and TGFBRs, in prostate adenocarcinoma specimens." (PMID 36552758, 2022).
rectal cancer (3 papers, 2018 to 2021). A primary or metastatic malignant neoplasm that affects the rectum. "Taken together, our study revealed that OCT4 conferred radio-resistance in human rectal cancer cells by promoting EMT process in a ZEB1 dependent manner for the first time." (PMID 30112378, 2018). "In conclusion, our results indicated that OCT4 can confer radiation resistance and migration activity of human rectal cancer cells by enhancing EMT in ZEB1 dependent manner for the first time." (PMID 30112378, 2018). "Although ZEB1 was upregulated by OCT4, the exact roles of ZEB1 in radiation resistance of human rectal cancer remained unknown." (PMID 30112378, 2018). "But, whether and how ZEB1 could influence the components of DNA damage repair machine in rectal cancer cells remain to be further confirmed." (PMID 30112378, 2018). "According to literature validation, we detected some rectal cancer‐related mRNAs including PRKCB, NCAM1, ZEB1, PCDH7, Cav1 and FGF2 in the subnetwork." (PMID 34613665, 2021). "More interestingly, CHK1 was also upregulated in OCT4/ZEB1 dependent manner conferring stronger DNA damage repair activity on cancer cells, which might explain the underlying mechanisms why OCT4/ZEB1 axis could promote the resistance of human rectal cancer cell to radiation." (PMID 30112378, 2018). "By improving epithelial‐mesenchymal transition in a ZEB1‐dependent manner, OCT4 could enhance radio‐resistance development in rectal cancer cells." (PMID 34613665, 2021).
silicosis (3 papers, 2022 to 2025). Silicosis is a respiratory disease caused by breathing in (inhaling) silica dust. "The results revealed a reduction in the epithelial marker E-Cad, while the expression levels of the mesenchymal markers α-SMA, Vimentin, and ZEB1 were notably elevated in the lung tissue of silicosis mice." (PMID 40423444, 2025). "In addition, a previous study established a silicosis mouse model and an in vitro EMT model of A549 cells and found that lncRNA UCA1 might regulate the EMT process by competitively adsorbing miR-204-5p to release its target gene ZEB1." (PMID 36494831, 2022).
Stroke (3 papers, 2009 to 2024). Sudden impairment of blood flow to a part of the brain due to occlusion or rupture of an artery to the brain. "The ischemic increase in ZEB1 results, in part, through transcriptional induction by p63, itself induced early in response to stroke." (PMID 19194497, 2009). "Similar levels of induction of human ZEB1 protein are seen in cortical samples derived from pathology specimens of stroke victims." (PMID 19194497, 2009). "The stroke-induced increase in ZEB1 mRNA and protein levels in cortical neurons is both developmentally and phylogenetically conserved and may therefore be part of a fundamental cellular response to this insult." (PMID 19194497, 2009). "Specifically, we demonstrate that ZEB1 protein expression levels in cortical neurons in vivo are highly induced early in response to the experimental administration of permanent unilateral stroke in both the developing and mature brain." (PMID 19194497, 2009). "We then asked whether ZEB1 is similarly regulated in vivo as a consequence of experimentally-induced stroke." (PMID 19194497, 2009). "After stroke, PATJ depletion triggers the loss of cell polarity that may explain YAP/TAZ translocation to the nucleus, which we observed it was accompanied by MUC1-C together with β-catenin and ZEB1." (PMID 38368420, 2024).
T-cell deficiency (3 papers, 2018 to 2023). "As the germline knockout mouse of ZEB1 is lethal due to skeletal defects and severe T cell deficiency in the thymus, and in order to exclude the chance of insufficient transient knockdown, a complete knockout was made in Hs578T cells using CRISPR‐CAS9 gene editing technology." (PMID 29744893, 2018). "Interestingly, Zeb1 null mice do not survive postnatally due to respiratory failure and T-cell deficiency." (PMID 36862248, 2023).
T-cell lymphoma (3 papers, 2015 to 2022). "ZEB1 mutant mice confirmed the importance of this alteration by frequently developing invasive CD4+ T-cell lymphomas; additional in vitro studies showed the loss of ZEB1 expression in ATLL cells resulted in an escape from growth inhibition by TGF-β." (PMID 32309604, 2018).
thyroid tumor (3 papers, 2020 to 2024). A benign or malignant neoplasm affecting the thyroid gland. "Lastly, ZEB1 silencing decreased the ability of thyroid tumoral cells to migrate and invade, pointing to its importance in thyroid tumor mestastases." (PMID 31846430, 2020). "We explored the molecular mechanisms underlying these effects, finding that the tumor suppressor miR-200b is overedited in thyroid tumors, and that RNA editing impairs its ability to inhibit the epithelial–mesenchymal transition (EMT) marker ZEB1." (PMID 32157211, 2020).
urothelial carcinoma (3 papers, 2018 to 2022). A malignant neoplasm derived from the transitional epithelium of the urinary tract (urinary bladder, ureter, urethra, or renal pelvis). "Here we report a patient with a plasmacytoid urothelial carcinoma of the renal pelvis whose plasmacytoid component was ZEB1 positive as determined by immunohistochemistry." (PMID 33032610, 2020). "Another possibility is the finding in urothelial carcinoma that invasive properties were significantly correlated to the up-regulated expression of ASMA in stromal fibroblasts and loss of membranous E-cadherin and increased Snail, Slug, Zeb1 in cancer cells." (PMID 29347950, 2018). "ZEB1 is another well-known inducer that promotes tumor invasion and migration by inducing EMT in carcinoma cells and is involved in metastasis and therapy resistance in cancers, including urothelial carcinoma." (PMID 35205628, 2022). "The noninvasive urothelial carcinoma was positive for cytokeratin and E–cadherin, and negative for vimentin and ZEB1." (PMID 33032610, 2020).
uterine cancer (3 papers, 2009 to 2019). Primary or metastatic malignant neoplasm involving the uterine corpus and/or the cervix. "ZEB1 is a protein implicated in the progression of lung, colon and uterine cancers, and it is controlled by the miR-200 family and miR-20566–68." (PMID 31417117, 2019).
vitamin D deficiency (3 papers, 2019 to 2023). A nutritional condition produced by a deficiency of VITAMIN D in the diet, insufficient production of vitamin D in the skin, inadequate absorption of vitamin D from the diet, or abnormal conversion of vitamin D to its bioactive metabolites. "In addition, vitamin D deficiency aggravated BLM-induced elevation of ZEB1-positive cells in the lungs." (PMID 31775746, 2019).
aneurysm (2 papers, 2019 to 2024). Bulging or ballooning in an area of an artery secondary to arterial wall weakening. "Higher ZEB1/ZEB2 expression, as well as a lower expression of the miR‐200 family, is compatible with an ongoing EndMT/EMT process in BAV that is aneurysm independent, and the transition to aneurysm state is most probably due to the further exasperation of a pre‐existing EndMT/EMT." (PMID 30280445, 2019). "Thoracic aneurysm SMCs shared TFs with thoracic aorta SMCs, such as Zeb1 and Atf6, which are not shared with abdominal aorta or aneurysm SMCs, suggesting these TFs may induce anatomic location-specific signals." (PMID 39590192, 2024).
biliary tract cancer (2 papers, 2021 to 2023). "Similarly, knockdown of ELF3 in biliary tract cancer cells resulted in upregulation of mesenchymal markers such as ZEB1/2, VIM and TWIST1 accompanied by the downregulation of KRT19." (PMID 36864480, 2023). "In conclusion, miR-200c-3p might be an important contributor to cisplatin resistance in biliary tract cancer, independently of its interaction with ZEB1." (PMID 34439151, 2021).
bladder tumors (2 papers, 2013 to 2021). "The abnormal expression of ZEB1 in BLCA is related to the differentiation and metastasis of bladder tumours." (PMID 34418989, 2021).
cardiac hypertrophy (2 papers, 2017 to 2023). "Here the authors uncover a pathway whereby AGGF1 blocks ER stress by inhibiting ERK1/2 activation and the transcriptional repressor ZEB1, leading to induction of miR-183-5p and down-regulation of CHOP, and show that AGGF1 can effectively treat cardiac hypertrophy and heart failure." (PMID 28743963, 2017).
cervical squamous cell carcinoma (2 papers, 2024 to 2025). A squamous cell carcinoma arising from the cervical epithelium. "Our previous study showed that hypoxia increased the expression of ZEB1 in cervical squamous cell carcinoma (CSCC) cells, which resulted in increased infiltration of TAMs." (PMID 38183060, 2024).
chronic obstructive pulmonary disease (2 papers, 2024 to 2025). A chronic and progressive lung disorder characterized by the loss of elasticity of the bronchial tree and the air sacs, destruction of the air sacs wall, thickening of the bronchial wall, and mucous accumulation in the bronchial tree. "In addition, a recent study demonstrated that GLUT3-mediated cigarette smoke-induced epithelial mesenchymal transition in chronic obstructive pulmonary disease through the NF-kB/ZEB1 pathway." (PMID 40413536, 2025).
corneal opacities (2 papers, 2010 to 2025). "Based on the observations of decreased gene expression levels, association with ZEB1 -related pathways, and the report of corneal opacities in heterozygotes and embryonic lethality in the null, we postulate that haploinsufficiency of Csrp2bp is responsible for the mouse PPCD1 phenotype." (PMID 20808945, 2010).
cutaneous T cell lymphoma (2 papers, 2022 to 2023). "In cutaneous T-cell lymphoma, upregulation of HDAC1 and HDAC6 was detected as a result of excessive autocrine production of IL-15 driven by disruption of the Zeb1 transcription factor binding to the IL-15 promoter." (PMID 35887172, 2022).
deafness (2 papers, 2011 to 2020). An inherited or acquired condition characterized by the complete loss of the ability to hear from one or both ears. "The association of misregulation of the ZEB1/miR-200b pathway with auditory and vestibular defects in the Twirler mutant mice uncovers a novel mechanism underlying deafness and balance disorders." (PMID 21980309, 2011). "Finally, utilizing the example of the ZEB1/miR-200b pathway, we present a proof-of-concept that cell type–specific gene expression profiles can be used to identify molecular pathways upstream and downstream of deafness genes." (PMID 21980309, 2011).
ductal breast carcinomas (2 papers, 2011 to 2017). "The transcriptional activity of E-cadherin can be negatively regulated by a multitude of transcriptional repressors like SNAIL, with expression levels increased in ductal breast carcinomas, but also Slug, zinc finger E-box-binding homeobox 1 (ZEB1), and ZEB2." (PMID 29231860, 2017). "Our results showed a lower expression of zeb1 in stromal cells in mucinous and medullary carcinomas than was the case in ductal carcinomas." (PMID 21324165, 2011). "Medullary carcinomas (p = 0.017) and mucinous carcinomas (p = 0.009) had a lower stromal expression of zeb1 than ductal carcinomas." (PMID 21324165, 2011).
epilepsy (2 papers, 2017 to 2025). A brain disorder characterized by episodes of abnormally increased neuronal discharge resulting in transient episodes of sensory or motor neurological dysfunction, or psychic dysfunction. "The Zeb-1-neuroinflammation axis plays an important role both in epileptogenesis and in the development of MetS in patients with epilepsy and epileptic syndromes receiving ASMs." (PMID 40217882, 2025).
Fanconi anemia (2 papers, 2021). Fanconi anemia (FA) is a hereditary DNA repair disorder characterized by progressive pancytopenia with bone marrow failure, variable congenital malformations and predisposition to develop hematological or solid tumors. "Increased VWF has been implicated in vascular dysfunction and decreased UBE2T in Fanconi anemia, and acute deregulated expression of these genes may have contributed to the adverse outcomes observed within 2 weeks of Zeb1/2 deletion." (PMID 34550965, 2021).
Fuchs' endothelial dystrophy (2 papers, 2018 to 2022). Fuchs endothelial corneal dystrophy (FECD) is the most frequent form of posterior corneal dystrophy and is characterized by excrescences on a thickened Descemet membrane (corneal guttae), generalized corneal edema, with gradually decreased visual acuity. "Multiple genetic loci have been linked to Fuchs' endothelial dystrophy, including but not limited to TCF4, COL8A2, SLC4A11, ZEB1 and LOXHD1." (PMID 29685994, 2018).
glaucoma (2 papers, 2024 to 2025). Increased pressure in the eyeball due to obstruction of the outflow of aqueous humor. "In the context of glaucoma, XFG and fibrosis, especially the process of EMT is relevant in which ZEB1 plays an important role." (PMID 39883689, 2025).
helminth infection (2 papers, 2018 to 2025). "Among these, ZEB1 has been described during helminth infection, where TLR9 stimulation increased ZEB1 expression in cDC1 dendritic cells." (PMID 40871238, 2025). "Besides that, adoptive transfer of Zeb1 KD cDC1 MutuDCs clears helminth infection by inducing IL-13 and IL-5 secreting Th2 cells in MLNs of infected animals." (PMID 30483264, 2018). "However, the animals treated with CpG pulsed Zeb1 KD DCs were almost free of helminth infection in the intestine as compared to control DC treated mice at D31." (PMID 30483264, 2018). "In addition, in Zeb1 KD DCs treated mice the intestines were almost clear of helminth infection as no or only few worms were found in the intestine depicted by the drastically reduced number of eggs on D31." (PMID 30483264, 2018).
inflammatory breast carcinoma (2 papers, 2022 to 2024). An advanced, invasive breast adenocarcinoma characterized by the presence of distinct changes in the overlying skin. "In inflammatory breast cancer (IBC), activated T cells could release soluble factors (TNF-α, IL-6, and TGF-β) to facilitate the expression of EMT-related genes, including FN1, VIM, TGM2 and ZEB1, thereby promoting EMT." (PMID 35251963, 2022).
injury (2 papers, 2009 to 2022). Damage inflicted on the body as the direct or indirect result of an external force, with or without disruption of structural continuity. "Second, in addition to permanent FCI, does ZEB1 play a role in other types of hypoxic-ischemic-mediated injury, in particular ischemia/reperfusion injury (i.e. in the context of increased reactive O2 species in vivo) and traumatic brain injury, as well as in other neuro-degenerative diseases?" (PMID 19194497, 2009). "The co-IP results reveal an increase in the protein binding rate of RUNX3-ZEB1 on MA exposure, which indicated the increase in PPIs between RUNX3 and ZEB1 in MA-induced chronic lung injury." (PMID 36479199, 2022).
interstitial lung disease (2 papers, 2014 to 2017). A diverse group of lung diseases that affect the lung parenchyma. "A recent study revealed that the ZEB1 gene is overexpressed in the lung tissues from patients with interstitial lung disease." (PMID 25358403, 2014). "Furthermore, there is a report that ZEB1 gene is overexpressed in the lung tissues of interstitial lung disease patients." (PMID 25358403, 2014). "In the interstitial lung diseases (ILD) study, it was reported that ZEB-1 affects the persistence of disease in ILD through suppression of NEDD4L by miR-23a." (PMID 28362846, 2017).
ischemia (2 papers, 2009 to 2023). A hypoperfusion of the BLOOD through an organ or tissue caused by a PATHOLOGIC CONSTRICTION or obstruction of its BLOOD VESSELS, or an absence of BLOOD CIRCULATION. "We have presented compelling evidence that ZEB1 induction is part of a protective response by neurons to ischemia." (PMID 19194497, 2009). "The data presented here provide the first evidence that ZEB1 induction is part of a protective response by neurons to ischemia." (PMID 19194497, 2009). "If ZEB1 functions, at least in part, as an early defense mechanism initiated in cortical neurons to promote their survival following ischemia, ZEB1−/−neurons in culture might be more vulnerable to the approximate tissue culture equivalent, oxygen-glucose deprivation (OGD)." (PMID 19194497, 2009).
laryngeal carcinoma (2 papers, 2020 to 2022). Carcinoma that arises from the laryngeal epithelium. "An additional possibility for reducing the expression of ZEB1 is inhibition of non-coding circular RNA (circRNA) hsa_circ_0057481, as shown in laryngeal cancer." (PMID 32266287, 2020).
laryngeal squamous cell carcinoma (2 papers, 2022). A squamous cell carcinoma that arises from the larynx. "OIP5-AS1 was reported to enhance the proliferation, motility activity and EMT via decoying miR-204-5p and increasing ZEB1 in laryngeal squamous cell carcinoma." (PMID 35756672, 2022).
liver diseases (2 papers, 2019 to 2021). "In the immunohistochemicalanalysis, the vimentin, TWIST and ZEB1 expression were significantly higher in theliver tumor than in other liver diseases (p=0.002, p<0.001, p=0.016,respectively)." (PMID 31038558, 2019).
malignant meningioma (2 papers, 2020 to 2022). "Conversely, lncRNA LINC00702 can activate Wnt/β-catenin signaling pathway by sponging miR-4652-3p to induce ZEB1 and promote the metastasis and invasion of malignant meningioma." (PMID 32664703, 2020). "In malignant meningioma, miR-4652-3p down-regulates the expression of ZEB1 by suppressing Wnt and nuclear translocation of β-catenin." (PMID 32664703, 2020).